BIRC5 (baculoviral IAP repeat containing 5)
Diseases named in the same sentence as BIRC5 in open-access papers (continued):
Sharing a sentence is not in itself a finding about the gene and the disease.
penile cancer (5 papers, 2017 to 2023). A primary or metastatic malignant neoplasm that affects the penis. "In penile cancer (PC), the silencing BIRC5 inhibits the inflammatory tumor microenvironment (ITM) and the progression of penile cancer." (PMID 36292719, 2022). "In in vitro and in vivo studies, penile cancer cell proliferation, migration, and invasion were all boosted by BIRC5 overexpression, while these same actions were reduced by BIRC5 knockdown." (PMID 36358602, 2022). "In our study, BIRC5 gene copy number gain and downexpression of hsa-miR-135a and hsa-miR-320 were significantly associated with increased expression levels of BIRC5 suggesting that multiple events could be involved with the aberrant activity of this gene in penile cancer." (PMID 28751665, 2017). "Thirdly, although BIRC5 does affect the development of tumor by affecting the tumor microenvironment in lung and penile cancer, our findings also predicted that BIRC5 may affect immune infiltration in PCa." (PMID 37077837, 2023). "However, the role of BIRC5 in penile cancer (PC) and the ITM-induced abnormal progression of PC is still obscure." (PMID 35461228, 2022). "In addition to the potential driver genes herein described, shorter overall survival was associated with BIRC5 and DNMT3B overexpression (log-rank test, P = 0.026 and P = 0.002, respectively) highlighting its potential as novel prognostic marker for penile cancer." (PMID 28751665, 2017).
acute lymphoblastic leukemia (4 papers, 2008 to 2021). Leukemia with an acute onset, characterized by the presence of lymphoblasts in the bone marrow and the peripheral blood. "It has also been reported that KLF5 up-regulated anti-apoptotic BIRC5 in human pulmonary vascular smooth muscle cells and acute lymphocytic leukemia cell lines." (PMID 26474386, 2015). "JQ1 downregulated c-Myc and Birc5 expression in primary paedriatric B-precursor acute lymphoblastic leukemia (B-precursor ALL) and sensitized the malignant cells to dexamethasone-induced apoptosis." (PMID 26405162, 2015).
autoimmune disease (4 papers, 2021 to 2025). A disorder resulting from loss of function or tissue destruction of an organ or multiple organs, arising from humoral or cellular immune responses of the individual to their own tissue constituents. "Several studies showed that Bcl2a, Birc5, and Il20rb were associated with chronic inflammation and autoimmune diseases, suggesting that inflammation could be one of the factors to drive the early capillary dropout." (PMID 40868180, 2025). "In contrast, Birc5 is overexpressed in numerous malignant diseases, as well as in autoimmune diseases, including multiple sclerosis and myasthenia gravis." (PMID 33557010, 2021). "The dysfunction in suppressing proinflammatory cytokine secretion and Birc5 upregulation in Dsg3-specific autoreactive T cells may reflect an aspect of the preliminary steps in autoimmune disease development in the aged population." (PMID 37308897, 2023). "CD274 (PD-L1), CXCL13, BIRC5, and SMPD3 play the following roles in the IL-17a and IL-23 pathways: CD274 (PD-L1): The IL-17a and IL-23 pathways are closely related to the pathogenesis of autoimmune diseases like psoriasis." (PMID 40557155, 2025). "For instance, Bcl2l2 and Birc5 expression was observed throughout the small pre-B cell stage but it was lost in immature B cells in mice without an autoimmune disease genetic background." (PMID 33557010, 2021).
cholangiocarcinoma (4 papers, 2016 to 2022). A carcinoma that arises from the intrahepatic biliary tree (intrahepatic cholangiocarcinoma) or from the junction, or adjacent to the junction, of the right and left hepatic ducts (hilar cholangiocarcinoma). "A consistent increase in the expression of survivin (BIRC5 gene), a member of the inhibitor of apoptosis protein (IAP) family, has been found in liver tumors, such as HB, HCC and cholangiocarcinoma (CCA)." (PMID 30909445, 2019).
COVID-19 (4 papers, 2021 to 2023). A disease caused by infection with severe acute respiratory syndrome coronavirus 2. "First, we compared the expression levels of five genes in COVID-19 and controls, finding that the expression of BIRC5, DTL, and NDC80 increased in COVID-19 while DNAJC4 and LILRB2 decreased." (PMID 37426635, 2023).
invasive ductal carcinoma (4 papers, 2013 to 2020). "For example, RBBP7 (RbAp46) and BIRC5 (survivin) expression in carcinoma cells is significantly higher in estrogen receptor (ER)-positive pure DCIS than in invasive ductal carcinoma (IDC)." (PMID 32156290, 2020).
kidney cancer (4 papers, 2021 to 2024). Primary or metastatic malignant neoplasm involving the kidney. "Our results show that high BIRC5 expression is associated with worse prognosis in all three analyzed types of kidney cancer." (PMID 35331169, 2022).
oral cancer (4 papers, 2017 to 2024). "In this study, we have developed a novel siRNA-based therapeutic strategy targeting BCL2 and BIRC5 for oral cancer." (PMID 31744202, 2019). "Here, polyethyleneimine (PEI)-modified magnetic Fe3O4 nanoparticles were prepared for the delivery of therapeutic siRNAs targeting B-cell lymphoma-2 (BCL2) and Baculoviral IAP repeat-containing 5 (BIRC5) into Ca9-22 oral cancer cells." (PMID 31744202, 2019). "Increased expression of the anti-apoptotic regulator Birc5 (survivin) is one mechanism by which oral cancer cells resist apoptosis." (PMID 29109723, 2017). "Targeting Birc5 is therefore a promising strategy for oral cancer therapy." (PMID 29109723, 2017). "BIRC5 is rarely mutated in oral cancer samples and upregulated compared to non-cancerous tissue." (PMID 31744202, 2019). "In this study, we prepared Fe3O4 nanoparticles and design siRNAs targeting BCL2 and BIRC5, aiming to explore the efficient delivery of therapeutic siRNA into oral cancer cells by Fe3O4 nanoparticles, which might provide a novel strategy for the future therapy of oral cancer." (PMID 31744202, 2019).
oral squamous cell carcinoma (4 papers, 2020 to 2025). "We found that the inhibition of the CBP/β-catenin axis mediated by ICG-001 in oral squamous cell carcinoma led to the downregulation of BIRC5, EZH2, AURKA, CCNA2, and other genes previously implicated in therapy resistance." (PMID 41227355, 2025). "Moreover, reduced expression of BIRC5 by Salinomycin and xanthohumol enhances radiotherapy sensitivity of NPC and oral squamous cell carcinoma cells, respectively." (PMID 36450751, 2022).
retinoblastoma (4 papers, 2014 to 2026). A malignant tumor that originates in the nuclear layer of the retina. "The study also mentions the connection between BIRC5 (survinin) and DNA methylation in retinoblastoma regulated by Dnmt1, Dnmt3a, and Dnmt3b." (PMID 41150792, 2025). "Exposure to carboplatin, topotecan, or radiation resulted in the elevated expression of BIRC5 in the retinoblastoma cell line." (PMID 35664300, 2022). "The role of BIRC5 in retinoblastoma has also been investigated before." (PMID 35664300, 2022). "Our results demonstrated that STAT3 activation induced up-regulation of BCL2, BCL2L1, BIRC5, and MMP9 genes in retinoblastoma cells." (PMID 25359779, 2014). "Furthermore, target genes of STAT3 including BCL2, BCL2L1, BIRC5, and MMP9 are up-regulated in retinoblastoma cells compared to other retinal constituent cells." (PMID 25359779, 2014).
B-cell Lymphoma (3 papers, 2020 to 2025). "A proteome profiling carried out on BRCA1-mutated W780 and W0069 cells evidenced that CDDO-Im significantly increases caspase 3 cleavage, increases heat shock protein 70 (HSP70), and decreases in claspin, BIRC5, B-cell Lymphoma-extra-large, and BCL2 associated agonist of cell death." (PMID 40136510, 2025). "Studying the relationship between ETV6 and BIRC5 in established high-grade B-cell lymphoma cell lines revealed an inverse relationship between these two proteins." (PMID 35053500, 2022). "Strikingly, the analyses of mixed B-NHL datasets evidenced that both YY1 and BIRC5 were significantly and highly overexpressed in BLs and high-grade B-NHLs, compared to their expression in other milder forms of B-cells lymphomas." (PMID 32899428, 2020). "Once again, the analysis showed that among the mature aggressive B-cell lymphomas, BLs, BLs-like were the tumor subtypes with a significantly higher expression of both YY1 and BIRC5." (PMID 32899428, 2020).
chordoma (3 papers, 2021 to 2022). Chordomas are rare malignant tumors arising from embryonic remnants of the notochord in axial skeleton. "Several recent studies (including our own) have revealed that EGFR-signaling dysbiosis modulated by CMTM3 and cMET exacerbated the chordoma process, and that DEPDC1B regulated ubiquitination of BIRC5 also promoted chordoma progression." (PMID 36248973, 2022). "On the other hand, upon the treatment of CHX (0.2 mg/mL, protein synthesis inhibitor), the protein stability of BIRC5 in shCtrl and shDEPDC1B chordoma cells was examined, indicating that DEPDC1B silencing induced a decrease of BIRC5 protein stability." (PMID 34330893, 2021). "The BIRC5+shDEPDC1B group can reduce the inhibitory effect of shDEPDC1B+NC-BIRC5 group in chordoma cells (P < 0.05)." (PMID 34330893, 2021). "As a consequence, BIRC5 was preliminarily identified as a downstream target of DEPDC1B in chordoma cells." (PMID 34330893, 2021). "Meanwhile, BIRC5 overexpression reduced the inhibitory effects of DEPDC1B knockdown in chordoma cells." (PMID 34330893, 2021). "Importantly, apoptosis repeat-containing 5 (BIRC5) was considered to be the downstream target of DEPDC1B involved in the progression of chordoma." (PMID 34330893, 2021). "In conclusion, DEPDC1B regulates the progression of human chordoma through UBE2T-mediated ubiquitination of BIRC5, suggesting that it may be a promising candidate target with potential therapeutic value." (PMID 34330893, 2021). "Moreover, BIRC5 overexpression reduced the inhibitory effects of DEPDC1B knockdown in chordoma cells." (PMID 34330893, 2021). "BIRC5 was the most relevant to the proliferative phenotype of chordoma cells." (PMID 34330893, 2021). "DEPDC1B regulates the progression of human chordoma through UBE2T-mediated ubiquitination of BIRC5, which may be a promising candidate target in molecular therapy of chordoma patients." (PMID 34330893, 2021). "Therefore, overexpression of BIRC5 can reduce the inhibitory effect of DEPDC1B knockdown on the malignant behaviors of chordoma cells." (PMID 34330893, 2021). "Moreover, overexpression of BIRC5 can reduce the inhibitory effect of DEPDC1B knockdown on the malignant behaviors of chordoma cells." (PMID 34330893, 2021). "Therefore, the significant breakthrough that DEPDC1B regulates the progression of human chordoma through UBE2T-mediated ubiquitination of BIRC5 may provide a valuable target for molecular therapy of chordoma patients." (PMID 34330893, 2021). "Although abnormal expression of BIRC5 is significantly associated with tumor progression, the exact role and molecular mechanism of BIRC5 in chordoma have not been determined." (PMID 34330893, 2021). "Furthermore, simultaneous downregulation of BIRC5 and DEPDC1B may exacerbate the inhibitory effects of chordoma cells." (PMID 34330893, 2021). "Simultaneous downregulation of BIRC5 and DEPDC1B may exacerbate the inhibitory effects of chordoma." (PMID 34330893, 2021).
Cirrhosis (3 papers, 2023 to 2025). A chronic disorder of the liver in which liver tissue becomes scarred and is partially replaced by regenerative nodules and fibrotic tissue resulting in loss of liver function. "There was also been reported a significant overexpression of BIRC5 in HCC tissues, contrast to its near undetectability in tissues affected by cirrhosis." (PMID 40458412, 2025). "The results revealed that the expression level of BIRC5 was found to be independent of the history of cirrhosis and hepatitis among HCC patients." (PMID 37679418, 2023).
colon adenocarcinoma (3 papers, 2021 to 2022). "Aloin and piperine can inhibit proliferation of (colo)rectal cancer cells; the genes MYC and BIRC5, the expression of which is decreased by the two compounds, are otherwise overexpressed in colon adenocarcinoma." (PMID 34422220, 2021).
Lupus (3 papers, 2013 to 2023). "This might be an important mechanism for breakdown of tolerance, since PRL-enhanced BIRC5 expression correlated with an early onset of lupus symptoms." (PMID 24454471, 2013).
lymph node metastasis (3 papers, 2011 to 2022). "In GC, higher BIRC5 expression levels were also associated with poor prognosis including decreased survival and lymph node metastasis." (PMID 34044823, 2021). "BIRC5 expression in the serum of PC patients who suffered lymph node metastasis was dramatically higher than those in the non-metastasis group." (PMID 35461228, 2022).
mesothelioma (3 papers, 2022 to 2024). A usually malignant and aggressive neoplasm of the mesothelium which is often associated with exposure to asbestos. "Furthermore, lower expression of CDK7, AKT1, PARP1 (p < 0.1), CCND2 (cyclin D2), CDK2, CDK4, BIRC5 (survivin), PCNA and CDH2 (N-cadherin) (p < 0.005) have been shown to result in longer median survival of patients with mesothelioma." (PMID 36304150, 2022).
metastatic tumor (3 papers, 2015 to 2019). "The mean expression intensity analysis of the clinical prostate database showed an increased expression of BIRC5 in metastatic tumor samples and tumors with higher clinical Gleason scores." (PMID 25436980, 2015). "These values indicate that Birc5 expression is not unique to the metastatic disease, but can be targeted equally in metastatic and non-metastatic synovial sarcomas." (PMID 30909651, 2019).
Obesity (3 papers, 2011 to 2022). Accumulation of substantial excess body fat. "In addition, to the best of our knowledge, this is the first study to evidence sex differences in the expression of the SURVIVIN/BIRC5 oncogene associated with the state of obesity, which was detected even before the manifestation of a tumor mass in the liver." (PMID 36499327, 2022). "In conclusion, this study evidenced a similar pattern in the expression of most carcinogenesis-related genes in the liver, except SUVIVIN/BIRC5, which could be a predictive biomarker of liver carcinogenesis predisposition in male patients with obesity." (PMID 36499327, 2022). "The SURVIVIN/BIRC5 oncogene expression data were then segmented by the obesity and lean groups of rats, and an analysis was performed in relation to sex and adjusted for final fat mass." (PMID 36499327, 2022). "Specifically, significantly higher transcriptional levels of SURVIVIN/BIRC5 were detected in male rats with obesity than in female rats with obesity and lean rats, after adjusting for fat mass." (PMID 36499327, 2022). "Under these conditions, a previous analysis of SURVIVIN/BIRC5 expression in PBMCs revealed significantly higher levels in patients with obesity (p < 0.001), mirroring the results observed in the livers of rats." (PMID 36499327, 2022). "Interestingly, among the genes studied, we detected a relevant gender dimorphism in the obesity-related expression of the SURVIVIN/BIRC5 oncogene." (PMID 36499327, 2022). "Additionally, sexual dimorphism in SURVIVIN/BIRC5 expression was evaluated in the blood leukocytes of patients with obesity and normal weight healthy individuals to assess the translation from animal results to humans." (PMID 36499327, 2022). "Our data show that SURVIVIN/BIRC5 expression was particularly higher in males with obesity; therefore, the SURVIVIN/BIRC5 oncogene could be postulated as a potential biomarker of susceptibility to HCC in male patients with obesity." (PMID 36499327, 2022). "In this analysis, the interaction between the obesity phenotype and sex for the expression of SURVIVIN/BIRC5 was statistically significant (p = 0.026)." (PMID 36499327, 2022). "Other universal genes previously shown to be increased during the expansion of the β-cell during obesity or pregnancy such as Birc5, Igf1r and Rasgrp1 also failed to increase in PPARγ deficient ob/ob islets (POKO vs. WT) further suggesting an inability of POKO islets to proliferate at a young age." (PMID 22208362, 2011).
prostate tumors (3 papers, 2014 to 2023). "As for BIRC5, similarly, it is reportedly expressed at particularly high levels in prostate tumors characterized by infiltration of TAMs, suggesting its potential correlation with TAM infiltration." (PMID 37647439, 2023). "Oncomine expression analysis of the Grasso Prostate Dataset reveals that BIRC5 expression is significantly higher in prostate tumors than in the normal prostate gland, with the highest expression in castration resistant metastatic prostate carcinomas." (PMID 25248616, 2014).
psoriasis (3 papers, 2023 to 2026). An autoimmune condition characterized by red, well-delineated plaques with silvery scales that are usually on the extensor surfaces and scalp. "Our study revealed the association of BIRC5 with the pathogenesis of psoriasis, suggesting its potential involvement in regulating cell apoptosis and survival in psoriasis." (PMID 40557155, 2025). "BIRC5 is a gene that encodes a protein called survivin, and its abnormal expression in psoriasis may be related to the regulation of cell apoptosis and survival in the IL-17a and IL-23 pathways." (PMID 40557155, 2025). "The deletion of BIRC5 alleviated IMQ-induced psoriasis-like skin lesions, reduced the PASI scores, and decreased epidermal thickness." (PMID 42056221, 2026). "Psoriasis is characterized by abnormal keratinocyte proliferation and BIRC5, also known as survivin, plays a critical role in the pathogenesis of psoriasis." (PMID 42056221, 2026). "This is consistent with our study results and provides clues for further research into the functions and mechanisms of BIRC5 in the development of psoriasis." (PMID 40557155, 2025). "BIRC5 may play an important role in psoriasis pathogenesis because of its effects on apoptosis." (PMID 38129460, 2023). "However, the regulatory role of BIRC5 in psoriasis progression remains unclear." (PMID 42056221, 2026). "To elucidate the mechanisms by which BIRC5 regulates psoriasis, we used a mouse model of imiquimod (IMQ)-induced psoriasis characterized by psoriasis area and severity index (PASI) scores and epidermal hyperplasia." (PMID 42056221, 2026). "The ROC curves demonstrated that the expression levels of eight Hub Genes—POSTN, CD274, CD24, SERPINB3, CXCL13, SMPD3, BIRC5, and RAB27A—exhibited high accuracy (AUC > 0.9) in classifying the Psoriasis and Control groups." (PMID 40557155, 2025). "Some studies indicate that CD274 (PD-L1), CXCL13, BIRC5, and SMPD3 are important in the pathogenesis of psoriasis." (PMID 40557155, 2025). "In addition, BIRC5, NAMPT and BCL2 may affect the development of psoriasis by regulating autophagy." (PMID 38129460, 2023).
rectal cancer (3 papers, 2014 to 2021). A primary or metastatic malignant neoplasm that affects the rectum. "Increased expression of BIRC5, which encodes antiapoptotic protein survivin, has been associated with increased resistance to IR therapy in rectal cancer and is a potential drug target of lung cancer." (PMID 24170811, 2014). "Several of these miRNAs had direct associations with BIRC5, including miR-145-5p and miR-17-5p for all CRC and miR-150-5p and miR-196b-5p for rectal cancer specifically." (PMID 29516317, 2018). "The miRNAs that appear to directly target BIRC5 are miR-145-5p, miR-150-5p, miR-195-5p, and miR-650; both miR-145-5p and miR-150-5p were associated with better survival after diagnosed with CRC overall or with rectal cancer specifically when upregulated in CRC tumor tissue." (PMID 29516317, 2018).